CD274 (CD274 molecule)
Diseases named in the same sentence as CD274 in open-access papers (continued):
Sharing a sentence is not in itself a finding about the gene and the disease.
cancer (continued). "Several inhibitory immunoreceptors, including but not limited to CD28, CD80, CD86, CTLA4, CD276, and CD274, have been identified and studied in cancer in recent decades." (PMID 38831187, 2024). "Further, the mRNA expression level of HIF1A was found to be positively correlated with mRNA expression PD‐L1 (CD274) in a variety of cancer types in the TCGA cancer patient dataset." (PMID 38956900, 2024). "In the past few decades, extensive research has been accomplished in exploring immune surveillance, especially PD‐1/CD274 signaling that is involved in the development and progression of cancer." (PMID 38506253, 2024). "At day 5 post-challenge, we see that classical M2-like, pro-cancer markers Arg1, Marco, and Cd274 are downregulated." (PMID 37066426, 2024). "PD-L1, also known as CD274, is a cell surface protein that plays a significant role in immune response regulation by binding to T cells through PD-1, thereby suppressing cancer immunity, and serving as a signal to evade detection." (PMID 38590525, 2024). "PD-1, an immune checkpoint molecule on T cell surface, and its counterpart, PD-L1 (CD274) often overexpressed on cancer cell surface, form a binding interaction, which suppresses T cell proliferation and activation." (PMID 38388484, 2024). "The obtained results demonstrated significantly elevated levels of CD80, CD86, CD279 and CD274 expressing leukocyte populations in the cancer patient group, while the numbers of NK cells and CD8- and CD25-positive cells were decreased." (PMID 39456247, 2024). "Programmed cell death-ligand 1 (PD-L1, gene symbol: CD274) is extensively expressed in different malignant tumors, serving as a significant component of the B7 protein family." (PMID 38762481, 2024). "To explore the reasons for CD274’s different expression in tumors, we identified genomic alterations of CD274 in 33 cancers." (PMID 38166842, 2024). "Programmed death-ligand 1 (PD-L1, CD274), an immune checkpoint protein expressed on cancer cells and immune cells, interacts with its binding partner programmed cell death-1 (PD-1) to inhibit T cell proliferation and cytokine production." (PMID 39335579, 2024). "AKT2 was positively correlated with VEGFB and CD274, among others, highlighting its potential involvement in cancer immunology and therapy resistance mechanisms." (PMID 39063239, 2024). "Oncogenic signaling can also lead to the upregulation of immune-escape proteins in cancers, such as CD274, CD80 and CD86." (PMID 38840185, 2024). "Thirdly, cancer cells can express high-level immune checkpoint proteins, such as the programmed death ligand 1 (PD-L1) protein coded by the CD274 gene, to protect themselves from being attacked by the cytotoxic effector T cells." (PMID 38893094, 2024). "Using TCGA data, we assessed the levels of CD274 expression in 33 cancer samples matched with normal samples additionally." (PMID 38166842, 2024). "PD-L1, also known as B7-H1 or CD274, plays a pivotal role in the immunological landscape, particularly in cancer immunotherapy." (PMID 38474186, 2024). "We discovered that JAK2-mutated cancers displayed upregulated expression of immune checkpoint molecules (such as PDCD1, CD274, CTLA4, and TIGIT) compared with JAK2-wild tumors." (PMID 38200372, 2024). "Three ICB therapeutic biomarkers (MSI, TMB, and CD274) showed significant correlation with METTL1 in a few cancers." (PMID 39289775, 2024). "The expression of CD274/PDCD1LG2 is pivotal in immune cell infiltration in the TME across various cancers." (PMID 38833018, 2024). "In subsequent experiments, we focused on ferroptosis‐induced CD274 due to the high therapeutic impact of up‐regulation of PD‐L1 in cancer cells." (PMID 37026630, 2023). "PD-L1 (CD274) is expressed in cancer cells and the PD-L1 protein mediates the interaction between cancer cells and T cells, leading to the suppression of T cell activity and immune evasion by cancer cells." (PMID 37835395, 2023).
cancer (continued). "It is noteworthy that CD276 was significantly positively correlated with GARS1 in 24 types of cancer, while CD274 (PD-1) was significantly positively correlated with GARS1 in 15 types of cancer." (PMID 37404826, 2023). "The programmed death-ligand 1 (PD-L1) (CD274) is found upregulated in many cancers, and it binds to PD-1 (CD279) on T cells, which inhibits T cell activation." (PMID 37511215, 2023). "TCGA database analysis revealed a positive correlation between ATXN3 and CD274 in more than 80% of human cancers." (PMID 38038129, 2023). "PD‐L1 (CD274 gene) is upregulated in many cell types, including cancer cells, in response to pro‐inflammatory cytokines." (PMID 36515567, 2023). "CD274, encoding PD-L1, was observed significantly correlated with ADIPOR1 and ADIPOR2 in almost all the cancers." (PMID 36896172, 2023). "In support of this, mature CD274 (PD-L1+) neutrophils have been shown to exert suppressive effects on T cell function in various other diseases like cancer and HIV infection." (PMID 37026002, 2023). "Programmed cell death-ligand 1 (CD274, PD-L1), which can be expressed on the surface of cancer cells binds to programmed cell death protein 1 (PDCD1, PD-1) on an immune cell surface, which inhibits immune cell activity." (PMID 38022653, 2023). "Immune checkpoint inhibits (ICIs) therapy have dramatically improved outcomes of cancer patients in clinical practice, especially for PD-1 and PD-L1 (CD274)." (PMID 37386390, 2023). "Immune checkpoint inhibitors (ICIs) are novel drugs targeting programmed cell death protein 1-ligand 1 (PD-L1, synonym CD274, B7 homolog 1) or its receptor (PD-1, synonym CD 279), and are increasingly used in cancer therapy." (PMID 37547603, 2023). "Although rare, some cancer cell lines exhibited intrinsic sensitivity to AC484 in the absence of IFNγ, which correlated with increased expression of NFKBIZ, CD274 (which encodes PD-L1), SOCS3, HLA-E, and several other ISGs (top)." (PMID 37794185, 2023). "Studies in humans have shown that CD274 (PD-L1) expression level is crucial to the success of immune checkpoint inhibitor (ICI) therapy in different cancers." (PMID 36768373, 2023). "Immune checkpoint inhibitor therapy addressing the programmed death ligand 1 (PD-L1, CD274) is a promising therapeutic strategy for cancer patients." (PMID 37174103, 2023). "Second, analysis of the TCGA database revealed a statistically significant positive correlation between ATXN3 and CD274 expression in most types of human cancers." (PMID 38038129, 2023). "A growing number of studies have suggested that PD-L1 (CD-274) is involved in cancer-cell metabolic adaptations." (PMID 37193972, 2023). "It is well documented that the high expression of PDCD1 (PD‐1, CD279) and PD‐L1 (CD274) is closely related to bad prognosis in certain human cancers." (PMID 35634680, 2023). "Immune checkpoint inhibitors (ICIs) against the programmed death receptor 1 (PD-1) protein and its ligand PD-L1 (B7-H1, CD274) also have been a focus in cancer immunology and oncology." (PMID 37686163, 2023). "It has been reported that RT induces the upregulation of type I IFN, MHC class I and PD-L1 (CD274) in cancer cells, and several immune cells, such as CD8 + T cells, dendritic cells (DCs) and M1 macrophages, are attracted to tissues after RT2." (PMID 37543704, 2023). "Approximately 29%, 15%, and 12% of the critical miRNAs in these cancer types also negatively regulated CD274 expression in at least one of the other cancer types." (PMID 35289334, 2022). "Based on miRDB and miRabel databases, the recent Bioinformatic Exploratory Study identified 49 unique miRNA were identified across fourteen different cancers as potentially targeting PD-1 (PDCD1)/PD-L1 (CD274)." (PMID 36189271, 2022). "CD274 participates widely in the resistance of various cancers to treatment, such as chemotherapy and targeted therapies as an important immunosuppressive factor." (PMID 36483329, 2022).
cancer (continued). "Here, in mice engrafted with human PBMC we detected no significant increase in PD-L1 expression (FITC-conjugated anti-human CD274) in human cancer cells from mice given avelumab alone or SNS-032 plus avelumab." (PMID 35884422, 2022). "As the major ligand of PD-1, PD-L1 (known as CD274 or B7-H1) is expressed in malignant tumor cells, lymphocytes, antigen presenting cells (APC), hematopoietic cells and epithelial cells." (PMID 35784705, 2022). "Since TMB, MSI, DNMT and MMR expression were proved associated with the efficiency of checkpoint-blocked therapy across various cancer types, the relationships between CD274/PDCD1LG2 and these markers were examined." (PMID 36276934, 2022). "Overall, the prediction of CD274 expression gave similar results in cancer-specific models and the generalized model." (PMID 35289334, 2022). "miRNAs from the let-7, mir-10, mir-1276, mir-17, mir-196, and mir-203 families were found to be negative regulators of CD274 in all three cancer types." (PMID 35289334, 2022). "Our findings brought to light that PTX3 had a close and positive association with most ICIs (CD274, CTLA4, HAVCR2, LAG3, PDCD1, PDCD1LG2, TIGIT, and SIGLEC15) in TCGA cancers, except TGCT." (PMID 36139597, 2022). "Programmed death-ligand 1 (PD-L1 or CD274) is a protein expressed on the cell membrane of cancer cells that can bind with programmed death receptor 1 (PD-1 or CD279) expressed by infiltrated T cells." (PMID 35164673, 2022). "Successful treatment of many cHL patients using antibodies against programmed cell death 1 (PD-1; known as PDCD1) and its ligand (PD-L1; known as CD274) has highlighted the critical importance of PD-1/PD-L1-mediated immune escape in cancer development." (PMID 36140254, 2022). "The ROC curve was used to evaluate the diagnostic value of CD274 and PDCD1LG2 in pan-cancer analysis." (PMID 36276934, 2022). "Meanwhile, we also explored the associations between 8 common immune checkpoints and GCLM in pan-cancer, and found that GCLM tightly linked with the expression of immune checkpoints in cancers, especially the CD274 (also namely PD-L1)." (PMID 36353567, 2022). "AP3S1 expression was positively correlated with most immunosuppressive genes in pan-cancer, such as the common CD274 (PD-L1), PDCD1 (PD-1), CTLA4, LAG3, and TIGIT." (PMID 35874816, 2022). "In conclusion, we found IRF1 to be a general predictor for CD274 expression in all three studied cancer types, and STAT1, NFKB, HIF1A and BRD4 to be predictors for some of these cancer types." (PMID 35289334, 2022). "By way of addition, in this study, three ICB therapeutic biomarkers (MSI, TMB, as well as CD274) showed a significant correlation with METTL1 among a few cancers." (PMID 35432338, 2022). "PD-L1 also known as CD274 is a crucial immune check point protein that has been reported to be expressed on the surface of cancer cells as well as cancer cells derived EVs." (PMID 35624582, 2022). "The expression of inhibitory signals (checkpoints) by the cancer cell is an essential mechanism of immune evasion and can involve a number of inhibitory molecules such as PD-L1 (CD274), IDO, LAG3, TIM-3, VISTA, and others." (PMID 35515125, 2022). "PD-L1, also known as CD274, is a co-inhibitory receptor expressed on the surface of multiple cell types, including cancer cells." (PMID 35946310, 2022). "CD274, PDCD1, and CTLA-4 were known as critical immune checkpoints that are associated with immune escape in cancers." (PMID 36254230, 2022). "We used the final MLR models to predict CD274 expression for each individual patient and compared this to the actually observed CD274 expression in the 3 cancer types." (PMID 35289334, 2022). "The final model was highly significant (p = 2.2e−16), and for all three cancer types IRF1 was identified as a significant explanatory variable for CD274 expression (left 3 columns)." (PMID 35289334, 2022).
cancer (continued). "It is well known that CD274 plays an important immuno-suppressive role in various cancers, conferring immune evading capabilities to the expressing transformed cells." (PMID 35626630, 2022). "In the current study, we assessed the expression of CD274 and PDCD1LG2 and analyzed their associations with clinical characteristics across 33 cancer types." (PMID 36276934, 2022). "We therefore set out to quantify to what extent the PD-L1 mRNA level (CD274) in cancer patients can be predicted by activity of the relevant TFs MYC, HIF1A/2A, JUN, IRF1, STAT1/3, NFKB, and NRF2." (PMID 35289334, 2022). "Although a variety of previous studies have demonstrated the expression and functions of CD274 and PDCD1LG2 in certain cancer types, these studies tended to focus on individual cancer types, which restricted the co-analysis of CD274 and PDCD1LG2." (PMID 36276934, 2022). "The Programmed death-ligand 1 (PD-L1), also known as CD274 on cancer cells, contributes to cancer immune escape." (PMID 36251702, 2022). "The results revealed that spermine treatment significantly increased the CD274 mRNA and PD-L1 protein expression in these cancer cells." (PMID 36348350, 2022). "The MLR models developed so far were based on hundreds of patients per cancer type, which allowed us to identify differences in the importance of CD274-regulating TFs." (PMID 35289334, 2022). "To further test the prognostic value of high coexpression of CHRNA5 and CD274 in LUAD, we downloaded α5-nAChR and PD-L1 gene expression data from the cancer genomic browser of UCSC Xena." (PMID 35971127, 2022). "In most cancers, CD274 and PDCD1LG2 showed significantly positive relationship with memory-activated CD4+ T cells but a negative correlation with naive CD4+ T cells." (PMID 36276934, 2022). "AP3S1 expression was positively correlated with most immunosuppressive genes in pan-cancer, such as CD274 (PD-L1), PDCD1 (PD-1), CTLA4, LAG3 and TIGIT." (PMID 35874816, 2022). "By targeting the immune checkpoint in TME, anti-cytotoxic T-lymphocyte associated protein 4 (CTLA4), anti-programmed cell death 1 (PD-1), and anti-CD274/PD-L1havebeen shown to be the most effective immunotherapy methods for cancer." (PMID 34827528, 2021). "It has been well accepted that the ICI marker genes, PD-1 or CD274 (PD-L1), acts as important drug targets in cancer immunotherapy." (PMID 34897033, 2021). "Using CCLE and TCGA databases, a large number of diverse types of cancers are obtained, which contributes to discovering the abnormal CD274/PDCD1LG2 expression among the different types of cancers." (PMID 33833994, 2021). "Forty genes were consistently correlated with PDCD1/CD274 across multiple cancers, with the cancers themselves exhibiting a differential role for the correlated genes in terms of patient survival." (PMID 34067485, 2021). "Regarding specific cancer-associated genes, the CYT-high subgroup had more CNAs, including gains in NF1, CDK12, ERBB2, RARA, MDM4 and MYC; and losses in BRCA1, CD274 and APC." (PMID 34316699, 2021). "As the most well-known recent biomarker in the cancer research field, PD-L1, also named CD274, was found to be upregulated in IDH1/2 wild-type GBM." (PMID 33621203, 2021). "According to this study, the CD274/PDCD1LG2 level was related to the immune infiltration levels in cancers." (PMID 33833994, 2021). "This study utilized a bioinformatic approach to explore potential factors contributing to the PDCD1/CD274 network on a pan-cancer basis." (PMID 34067485, 2021). "Immunotherapy targeting immune checkpoints CTLA4 and PD-1/PD-L1 (CD274) have been used in cancer patients." (PMID 34249910, 2021). "This bioinformatic study interrogated molecular differences pertaining to PDCD1/CD274 and their correlated genes on a pan-cancer basis to identify differences between cancer types." (PMID 34067485, 2021).
cancer (continued). "Taken together, these results shed light on the varying PDCD1/CD274 networks between individual cancers and signpost a need for more cancer-specific investigations and treatments." (PMID 34067485, 2021). "In some cancers such as classical Hodgkin lymphoma and small-cell lung cancer, the copy number of chromosome 9p24.1 (where CD274 resides) was increased." (PMID 33413496, 2021). "Taken together, our findings provide clues for the association between CD274/PDCD1LG2 and cancer immunity, which require further experiment investigations to clarify." (PMID 33833994, 2021). "Collectively, our comprehensive pan-cancer analysis has characterized CD274/PDCD1LG2 in different cancer cell lines and tissues of seven gastrointestinal cancer types." (PMID 33833994, 2021). "CD4+ T cells co-cultured with MDA-MB-231 cancer cells during the restimulation period exhibited substantially increased proportion of CD274+ and CD273+ T cells in comparison to lymphocytes restimulated in the absence of cancer cells." (PMID 34439305, 2021). "MIR100HG was significantly correlated with the expression of CD200, CD274 and CD276 in pan‐cancers and was significantly associated with the abundance of central memory CD8 T cells, effector memory CD4 T cells and effector memory CD8 T cells in pan‐cancers." (PMID 33797188, 2021). "Among the potential targets of miR-766-5p, PD-L1 (CD274), an inhibitory immune receptor, has been identified as a key target of immunotherapy for cancers by various studies." (PMID 34425872, 2021). "PANX1 was shown to be positively associated with some immune inhibitors such as CD274, PDCD1LG2, and TGFBR1 in a variety of cancers." (PMID 34796785, 2021). "To compare TAM infiltration and PD-L1 expression in human GBM versus a wide range of other cancers, we analyzed the TCGA database for mRNA expression of two TAM-associated genes (CD163; PD-L1 [CD274]) and one T cell-associated gene (CD3E)." (PMID 34083417, 2021). "The cancer immunotherapy field has been revitalized with the discovery of immune checkpoints such as programmed cell death protein-1 (PD-1), and its ligand (PD-L1, CD274), that act as natural regulators of the immune system." (PMID 33608051, 2021). "The present work illustrated a comprehensive workflow for a pan-cancer analysis and thoroughly investigated the role of CD274/PDCD1LG2 in gastrointestinal cancers." (PMID 33833994, 2021). "Programmed cell death protein 1 ligand 1 (PD-L1), also known as cluster of differentiation 274 (CD274), is an immune system checkpoint regulator which has been implicated in various cancers." (PMID 34884984, 2021). "Genes correlating with PDCD1/CD274 across multiple cancers were taken forward for drug repurposing via DRUGSURV and microRNA analysis using miRDB and miRabel." (PMID 34067485, 2021). "Our findings confirmed that downregulation of BICD1 is a favorable prognostic marker and is highly correlated with downregulation of several important markers associated with cancer progression, including CD274 (PD-L1), in LGGs in the CGGA and CCLE datasets." (PMID 34439934, 2021). "PD-L1 (also known as CD274) is a cell-surface protein that is frequently upregulated in cancer cells." (PMID 34321074, 2021). "Immune checkpoint blockade targeting PD-1 (PDCD1)/PD-L1 (CD274) is increasingly used for multiple cancers." (PMID 34067485, 2021). "The immune checkpoint marker, programmed death-1 (PD-1), and its ligand, programmed death ligand-1 (PD-L1, CD274, B7-H1), have recently attracted interest in the field of cancer immunology." (PMID 34885101, 2021). "This exploratory study uses a bioinformatic approach to examine the impact of mRNA levels of PDCD1, CD274, and genes showing correlated expression levels on the survival outcome of a range of cancers." (PMID 34067485, 2021). "A pan-cancer analysis of CD274/PDCD1LG2 is valuable for identifying a differential expression and its role in many cancer types." (PMID 33833994, 2021).